CDK4 (cyclin dependent kinase 4)
Diseases named in the same sentence as CDK4 in open-access papers (continued):
Sharing a sentence is not in itself a finding about the gene and the disease.
breast cancer (continued). "Pivotal phase III trials in advanced breast cancer, where CDK4/6 inhibitors were administered in combination with endocrine therapy (e.g., aromatase inhibitor, fulvestrant), have revealed that palbociclib, ribociclib and abemaciclib were generally well tolerated." (PMID 34204543, 2021). "Therefore, the development of a CDK2-specific kinase inhibitor is a rational approach for the treatment of breast cancers that are resistant to CDK4/6 inhibitor." (PMID 33260316, 2020). "Thus, our study established the CDK4/6-USP51-ZEB1 axis as an important regulatory mechanism of breast cancer metastasis and provided a rationale for future therapeutic interventions in the treatment of advanced breast cancer." (PMID 32296027, 2020). "Furthermore, a previous study revealed that CDK4 and MDM2 mutations occurred in melanomas and liposarcoma, while ERBB2 mutations occurred in breast cancer, EGFR mutations occurred in astrocytoma, and MYCN mutations occurred in neuroblastoma." (PMID 32711494, 2020). "In addition, it was previously reported that PI3K/AKT/mTOR signaling pathway activation promotes cell cycle progression in CDK4/6 inhibitor resistant breast cancer cells through increased CDK2 and cyclin E." (PMID 32899250, 2020). "Therefore, inhibition of the CDK4/6 pathway has emerged as a promising strategy to treat HR-positive/HER2-negative breast cancer." (PMID 33260316, 2020). "A survey of promoter binding sequences disclosed that all genes in the amplicon possess several putative binding sequences in their promoters for ERα, ERβ and the transcription factor E2F1 which is a target of activation by the cyclin D/CDK4 cascade in breast cancer with high proliferation fraction." (PMID 32987805, 2020). "Taken together, our results provide evidence that the CDK4/6-USP51-ZEB1 axis plays a key role in breast cancer metastasis and could be a viable therapeutic target for the treatment of advanced human cancers." (PMID 32296027, 2020). "Some cell cycle regulators have been reported to be involved in not only breast cancer progression but also in the stem-like cell activity of breast cancer cells; for example, inhibition of cyclin D1 or CDK4/6 increases or decreases the migration capacity of stem cells in breast cancer." (PMID 32050983, 2020). "Previous reports showed that 20(S)-Rh2 could reduce the transcriptional activity of E2F by targeting cyclin D1 and CdK4/6, leading to G1/S cell cycle arrest and apoptosis in liver cancer and breast cancer cells." (PMID 32796841, 2020). "Deficiency of mismatch repair may lead to the endocrine therapy resistance in luminal breast cancer through the abrogation of CHK2-mediated inhibition of CDK4." (PMID 33364954, 2020). "Importantly, breast cancer cells that survive lapatinib treatment show enhanced activation of cyclin D1/CDK4 complex, hence suggesting the importance of this pair for anti-HER2 response and subsequent relapse." (PMID 32164162, 2020). "Previous studies have shown that activated PI3K/mTOR signaling may be playing a role in resistance to CDK4/6-based therapies in ER+ breast cancer." (PMID 32795346, 2020). "Collectively, these data suggest a complex interplay between PI3K, ER, and CDK4/6 signaling that may drive ER+/HER2− breast cancers to respond and then progress through currently approved therapies." (PMID 32795346, 2020). "Given that the EMT-inducing transcription factor ZEB1 plays an essential role in cancer cell plasticity and tumor recurrence, future studies should focus on the role CDK4/6-USP51 signaling plays in breast cancer initiation, aggressiveness and therapy resistance through ZEB1." (PMID 32296027, 2020). "Studies have shown that breast cancer cells activate autophagy in response to palbociclib, possibly through the inhibition of cyclin D1 expression, and the combination of autophagy and CDK4/6 inhibitors induces irreversible growth inhibition and senescence in vitro." (PMID 33364954, 2020).
breast cancer (continued). "In hormone-receptor-positive (HR+), human epidermal growth factor receptor 2-negative (HER2−) breast cancer CDK4/6 inhibitors and mammalian target of rapamycin (mTOR) inhibitors are the most widely used targeted therapies, adding significant benefit to baseline endocrine therapy." (PMID 32565737, 2020). "In particular, a recent preclinical study has suggested that targeting CDK7 could overcome CDK4/6 inhibitor resistance in HR-positive breast cancer." (PMID 33260316, 2020). "Therefore, the major emerging consideration in treatment of advanced luminal breast cancer is now CDK4/6 inhibitor resistance." (PMID 33364954, 2020). "Levels of molecular markers associated with cell-cycle progression, CDK4 and Cyclin D1, also decreased following PGRMC1 silencing, whereas the expression of pro-apoptotic markers, Bax and cleaved-caspase 3, increased in both breast cancer cell lines." (PMID 32704174, 2020). "Given that the standard-of-care for many ER+/HER2− breast cancers is now hormone therapy in combination with a CDK4/6 inhibitor, there is a strong rationale to suggest inhibitors of PI3K/mTOR signaling may also be active in this arena." (PMID 32795346, 2020). "Whether DILA1 plays a similar role in breast cancer that received the treatment of aromatase inhibitors or CDK4/6 inhibitors remains unknown and needs further study." (PMID 33139730, 2020). "Secondly, although pan-cancer analysis revealed that the combination of CDK4/6i and PARPi might potentially show synergy in multiple cancer types, the primary focus of the current study was on breast cancer." (PMID 32249776, 2020). "On the other hand, CDK4/6 which are amongst the genes rarely mutated in our cohort of study, have been known to play a key role in the proliferation of both normal breast epithelium and breast cancer cells, and therapies based on CDK4/6 inhibitors are suggested for certain types of breast cancer." (PMID 33319839, 2020). "However, similar strong preclinical evidence supported the potential of CDK4/6 inhibition in breast cancer treatment for many years, yet specific and efficient CKIs of CDK4/6 only became recently available." (PMID 35582046, 2020). "Alternatively, ER+/HER2− breast cancers may be treated with cyclin-dependent kinase CDK4 and CDK6 inhibitors (e.g., palbociclib, abemaciclib or ribociclib)." (PMID 32878084, 2020). "Clinical studies have demonstrated that addition of selective CDK4/6 inhibitor palbociclib to letrozole or fulvestrant showed an improvement in median progression-free survival (PFS) in patients with HR-positive advanced-stage breast cancer." (PMID 32792963, 2020). "These biomarkers with further extensive validation may serve as biomarkers for the CDK4/6 inhibitors that are currently available for breast cancer patients with hormone receptor-positive metastatic/advanced breast cancer." (PMID 33007815, 2020). "Our findings could pave the way for the development CDK2-specific kinase inhibitor for the treatment of breast cancers that are resistant to CDK4/6 inhibitor." (PMID 33260316, 2020). "CDK4/6 inhibitors such as ribociclib are becoming widely used targeted therapies in hormone-receptor-positive (HR+) human epidermal growth factor receptor 2-negative (HER2−) breast cancer." (PMID 32565737, 2020). "Recently, some breakthroughs of CDK4/6 inhibitor were made in treating breast cancer." (PMID 33009370, 2020). "However, despite the promising clinical advances with CDK4/6 inhibitors, 15% of the ER+/HER2− breast cancer patients show de novo or early CDK4/6 inhibitors resistance and 50% develop clinical resistance with progression within 25 months." (PMID 32164162, 2020). "Furthermore, other studies identified an estrogen-independent role for ER and CDK4/Rb/E2F transcriptional axis in the hormone-independent growth of breast cancer cells." (PMID 32210163, 2020).
breast cancer (continued). "Therefore, we propose that c-myc status will be useful as a predictive biomarker or indicator for the response to CDK4/6 inhibitors for the treatment of breast cancer." (PMID 32934206, 2020). "In addition, we performed transwell, wound-healing and 3D outgrowth invasion assays to demonstrate that the phosphorylation of Ser26-USP51 is able to mediate the cell migration and invasion induced by CDK4/6 in breast cancer cells in vitro." (PMID 32296027, 2020). "In luminal breast cancer, activation of ER is the major driver of CDK4/6." (PMID 33364954, 2020). "Additionally, other important endpoints, such as the response rate, time to chemotherapy, and a delay in quality of life deterioration, were positively impacted by CDK4/6 inhibitors’ addition to the treatment of advanced HR-positive breast cancer." (PMID 32882980, 2020). "We review various resistance mechanisms of CDK4/6 inhibitors in luminal breast cancer." (PMID 33364954, 2020). "In this context, preclinical data suggest that CDK4/6 inhibition may be effective in HER2-positive breast cancer and could restore sensitivity to anti-HER2 therapies." (PMID 32899866, 2020). "Indeed, we derived response models on a clinical cohort of breast cancer metastatic patients being treated with a combination of CDK4/6 and aromatase inhibitors, showing a good correlation with progression-free survival." (PMID 32907621, 2020). "Moreover, CDK4/6 inhibitors are currently being tested in ER+/HER2+ breast cancer and reported encouraging results." (PMID 32164162, 2020). "Collectively, our data show that the CDK4/6-USP51-ZEB1 axis might play a key role in breast cancer metastasis, which can serve as a basis for the future development of therapeutic interventions in the treatment of advanced cancers." (PMID 32296027, 2020). "In addition, either high or low expression of CDK4 has been detected in CDK4/6 inhibitor–resistant breast cancer cells." (PMID 33364954, 2020). "The repression of CDK4–CCND complex in ZR-75-1 cells by SFN may be realized through downregulation of SERTAD1gene expression with reducing the CDK4 activity in breast cancer cells." (PMID 31084542, 2019). "CaMKI controls the progression of MCF-7 breast cancer of cells through G1, potentially by regulating cdk4 and retinoblastoma protein (Rb) phosphorylation, as overexpression of the kinase-inactive CaMKI K49A mutant prevents cdk4 activation and Rb hyperphosphorylation in WI-38 fibroblasts." (PMID 30621060, 2019). "Our unexpected findings thus extend the initial application of CDK4/6 inhibitors in treating estrogen receptor-positive (ER+) breast cancers which are often characterized with dysregulated CDK4/6 activation, where the oncogenic addiction to cyclin D1 is being targeted." (PMID 30718506, 2019). "Second, ER expression status might determine the response of breast cancer cells to CDK4/6 inhibitors." (PMID 31100952, 2019). "In patients with type 1 neurofibromatosis associated with breast cancer, the expansion of CDK4 copy number may increase the expression of the NF1 gene and then up-regulate the expression of Her2 gene in breast cancer cells." (PMID 31358010, 2019). "Although cyclin-dependent kinase (CDK) 4/6 inhibitors have exhibited remarkable results for patients with estrogen receptor (ER)–positive breast cancer in clinical trials, the mechanism of CDK4/6 inhibitor resistance remains unclear." (PMID 31448056, 2019). "Inhibitors directed against the molecules CDK4/6, which are essential for the initiation and development of breast cancer and ALL, demonstrated growth inhibition in various cancers as well as induction of anti-tumor immunity by enhancing TAA expression and inhibiting regulatory T cell proliferation." (PMID 31178856, 2019). "This may be explained by the discovery of other critical targets for CDK4/6 in breast cancer growth and metastasis." (PMID 30720718, 2019).
breast cancer (continued). "Notably, combined PI3K and CDK4/6 inhibition, along with immune checkpoint inhibition induced durable regressions of TN breast cancer tumors in vivo." (PMID 31391067, 2019). "Similarly, artesunate up-regulated miR-34a expression in a dose-dependent manner, a well-known tumor suppressive miRNA, correlating with reduced CDK4 level in breast cancer cells." (PMID 31038546, 2019). "Among trials evaluating the efficacy of CDK4/6 inhibitors in patients with treatment-naïve HR+/HER2- advanced breast cancer, only PALOMA-2 included patients with brain metastases (2 of 666 enrolled participants), but only if they were previously treated and stable." (PMID 31695840, 2019). "CDK4/6 inhibitors are also promising in chemoresistant cases of HER2+-breast cancer." (PMID 31681564, 2019). "When CDK4/6 pathway is dysregulated, it leads to an implication in breast cancer biology." (PMID 30800400, 2019). "Future directions may also include defining subsets of HER2-positive breast cancer patients that are most likely to respond to CDK4/6 inhibition." (PMID 30959874, 2019). "The results of the analysis demonstrate that ribociclib plus letrozole treatment is both cost-saving and a cost-effective option amongst the available cyclin dependent kinase 4/6 inhibitors for the treatment of post-menopausal women with advanced breast cancer." (PMID 32685577, 2019). "In addition, CDK4/6 inhibitors are also considered in the early stage setting of HER2-positive breast cancer." (PMID 30959874, 2019). "The recent discovery that CDK4/6 inhibitors may have CNS activity in pre-clinical models is intriguing, raising the potential for an additional modality for the treatment of breast cancer brain metastases." (PMID 31695840, 2019). "The efficacy to CDK4/6 inhibitors is variable, depending on the breast cancer cell line." (PMID 31448056, 2019). "It will be important to determine whether the differences in the mechanisms of resistance to CDK4/6 inhibition observed in our studies of ER+ and ER− breast cancer cell models are also observed in patients receiving these regimens." (PMID 31100952, 2019). "Acquired CDK6 amplification has resulted in breast cancer resistance to CDK4/6 inhibitors; however, the reason for CDK6 overexpression resulting in resistance to CDK4/6 inhibitors remains unclear." (PMID 31448056, 2019). "However, recent studies indicated that exposure of RB1-intact breast cancer cells to a CDK4/6 inhibitor continuously prior to exposure to cytotoxic agents, such as doxorubicin and carboplatin, significantly reduced their cytotoxicity." (PMID 31600301, 2019). "Furthermore, the acute deletion of cyclin D1 or inhibition of CDK4/6 kinase activity using palbociclib blocked the progression of HER2-driven breast cancer in mice." (PMID 30959874, 2019). "Studies indicated that the inhibition of CDK2 and CDK4 enhanced autophagy in breast cancer cells." (PMID 30769922, 2019). "Thus, this study aimed to investigate the mechanism of CDK4/6 inhibitor resistance using two CDK4/6 inhibitor resistant breast cancer cell lines." (PMID 31448056, 2019). "Considering the central role of ER in driving the growth of ER+ breast cancers, and thus endocrine agents being a mainstay in the treatment paradigm, the effects of prior CDK4/6i exposure on ER signaling and the relevance of ER-targeted therapy are important to investigate." (PMID 31852484, 2019). "Despite the different contexts and molecular changes in each resistant derivative, elacestrant caused significant TGI, implying prior CDK4/6i treatment did not alter ER-dependent breast cancer cell growth and elacestrant activity in these contexts." (PMID 31852484, 2019). "Breast cancer patients often receive CDK4/6 inhibitors in combination with estrogen antagonists." (PMID 31101827, 2019).
breast cancer (continued). "These trials led to the approval of the first-in-class CDK4/6i, palbociclib, followed closely by the approval of two additional CDK4/6 inhibitors, ribociclib and abemaciclib, both in the first-line and second-line settings for ER+ advanced breast cancer." (PMID 31852484, 2019). "Similarly, palbociclib‐mediated growth inhibition cannot be fully recapitulated by knockdown of CDK4/6 in breast cancer cells." (PMID 29669860, 2018). "Recently, CDK4 inhibitors have successfully been used pre-clinically for the treatment of many human cancers, and in 2015, following the success of clinical trials, the FDA approved the first selective CDK4/6 inhibitor, palbociclib, for the treatment of endocrine therapy resistant breast cancers." (PMID 29670090, 2018). "Indeed, in murine breast cancer models, abemaciclib (CDK4/6i) + anti-PDL1 reduced tumor volume by 70% after ~2 weeks (stable up to 35 days) while abemaciclib or anti-PDL1 monotherapy was effective only temporarily." (PMID 30191140, 2018). "UC tumours may be inherently less sensitive to the cytostatic cell cycle arrest induced by palbociclib, either due to less dependence on CDK4/6 activity or resistance mechanisms from other pathway members that are less evident in breast cancer." (PMID 30293995, 2018). "Targeting the CDK4/6 pathway through treatment with CDK4/6 inhibitors in combination with letrozole has led to significant improvement in progression-free survival (PFS) compared with that achieved with single-agent ET in first-line HR+ breast cancer." (PMID 30340505, 2018). "The results in breast cancer, however, may also simply reflect the relative importance of CDK4/6 activity in breast cancer cell proliferation independent of Rb pathway genomic alterations." (PMID 30293995, 2018). "Below we summarize current approaches to targeted therapy in HR+/HER2+ breast cancer, highlight drug resistance mechanisms, and focus on CDK4/6 inhibitors as promising agents that may counteract therapeutic resistance in patients with HR+/HER2+ breast cancer." (PMID 30018827, 2018). "Thus, clinical trials have established that CDK4/6 inhibitors target luminal breast cancer cells which express ER." (PMID 29963233, 2018). "However, with recent advances in the treatment of metastatic/recurrent breast cancer, preserving patient QoL has become more manageable due to the availability of more tolerable agents, such as hormone therapy and CDK4/6 inhibitors." (PMID 29654415, 2018). "Preclinical studies in cell cultures and mouse models proved that CDK4/6i are active against a broad spectrum of solid tumors other than breast cancer, including liposarcoma, rhabdomyosarcoma, non-small cell lung cancer, glioblastoma multiforme, esophageal cancer, and melanoma." (PMID 30631751, 2018). "HER2-amlpified breast cancer cell lines are among the most sensitive to CDK4/6 inhibition." (PMID 29670855, 2018). "Indeed, apart from their use in combination with ET for the treatment of HR+ HER2– MBC, CDK4/6i are also under study as single agent in breast cancer (BC) and other solid tumors." (PMID 30631751, 2018). "Therefore, endocrine therapies and inhibitors targeting CDK4/6 activity are the core treatment modality in patients with HR+ advanced breast cancer." (PMID 28454587, 2017). "Moreover, in breast cancer cell lines, the CDK4 T172 phosphorylation best correlated with sensitivity to PD0332991." (PMID 28566333, 2017). "To further investigate whether the E2F cell cycle pathway was especially relevant in proneural GBM, we utilized palbociclib, a first-generation inhibitor of CDK4/6 recently approved by the FDA for breast cancer and now in clinical trials for patients with GBM." (PMID 28903422, 2017). "Taken together, these results reveal the importance of an intact G1/S transition for palbociclib response and provide a rationale for utilizing Rb in combination with LMWE as biomarkers of response to the combination of CDK4/6, aromatase and autophagy inhibitors in ER+ breast cancer." (PMID 28653662, 2017).